SDHAF2 (succinate dehydrogenase complex assembly factor 2)
Diseases named in the same sentence as SDHAF2 in open-access papers:
SDHAF2 is named in the same sentence as 44 diseases in open-access papers, as found by Europe PMC text mining. Sharing a sentence is not in itself a finding about the gene and the disease. The quoted sentences say what the papers report.
paraganglioma (27 papers, 2009 to 2025). A benign or malignant neoplasm arising from paraganglia located along the sympathetic or parasympathetic nerves. "Here, we present a patient diagnosed with multiple SDHAF2-linked head and neck paragangliomas who in addition developed paraganglioma metastases to the lung and spine and a primary or metastatic paraganglioma in the head of the pancreas." (PMID 38549682, 2024). "It has been confirmed that the mutation of the SDHAF2 gene can lead to hereditary paraganglioma-pheochromocytoma type 2." (PMID 31744495, 2019). "In this study, we showed that loss of maternal chromosome 11 is also a cardinal feature of SDHAF2-linked paragangliomas." (PMID 28099933, 2017). "Nonetheless, it is justified to screen for SDHAF2 mutations in young patients with isolated head and neck paragangliomas or in individuals with familial antecedents who are negative for other risk genes." (PMID 24899893, 2014). "In the same year, mutations in the SDHAF2 (SDH5) gene encoding a protein necessary for the flavination of the subunit SDHA were detected in patients with paraganglioma." (PMID 22995659, 2012). "Case 1 had Leu21 = -SDHAF2, AD inheritance of a paraganglioma-related gene variant." (PMID 34728707, 2021). "To further clarify the role of loss of the maternal copy of 11p in relation to loss of the long arm of chromosome 11 in paragangliomas, we used several genetic approaches to determine the allelic status of chromosome 11 in SDHAF2, SDHD, SDHB, and VHL mutant PGLs/PCCs." (PMID 28099933, 2017). "In addition to their role in primary mitochondrial disease, heterozygous germline variants in other complex II subunits and assembly factors (including SDHA, SDHB, SDHC, SDHD and SDHAF2) are associated with paragangliomas, phaeochromocytomas and gastrointestinal stromal tumours." (PMID 34012134, 2021). "VHL, RET, NF1, SDHB, and SDHD are major susceptibility genes, accounting for 90% of familial pheochromocytomas/paragangliomas, whereas TMEM127, SDHA, SDHC, SDHAF2, and MAX are minor susceptibility genes responsible for 10% of these tumors." (PMID 30456751, 2018). "In contrast to paraganglioma in SDHB and SDHC-linked families, both located on chromosome 1, in SDHD-linked families and in the recently described SDH5 (SDHAF2) family, only a mutation inherited via the paternal line results in tumorigenesis." (PMID 19956719, 2009). "Paraganglioma (PGL) is often linked with MEN, and its occurrence is commonly associated with metabolism-related mutation genes, which currently include SDHA, SDHB, SDHC, SDHD, and SDHAF2." (PMID 39591360, 2024). "The scarcity of SDHAF2 mutations was reinforced by the failure to document mutations in this gene among 315 patients with paraganglioma and without mutations in the SDHD, SDHC, or SDHB genes." (PMID 24899893, 2014). "The syndromic presentation of HNPGLs is associated with mutations in SDHD (paraganglioma syndrome type 1, PGL1), SDHAF2 (PGL2), SDHC (PGL3), SDHB (PGL4), SDHA (PGL5), VHL (von Hippel–Lindau syndrome), HIF-2α (paraganglioma–somatostatinoma–polycythemia), and NF1 (neurofibromatosis type 1 syndrome)." (PMID 39684472, 2024). "In a study of 972 cases from the European-American-Asian Pheochromocytoma and Paraganglioma Registry without mutations in the common PPGL genes, 58 had mutations in less commonly mutated genes (SDHA, TMEM127, SDHAF2) including 8 cases of PCC with MAX mutations." (PMID 31666924, 2019).
pheochromocytoma (24 papers, 2013 to 2025). "Though this relationship is not specifically related to a germline variant, RET, SDHB, SDHC, SDHD, and SDHAF2 each include a predisposition of developing pheochromocytoma and thus must be considered." (PMID 35685436, 2022). "In accordance with this model, several studies have confirmed the role of germline mutations in the SDHAF1 and SDHAF2 genes in the formation of head and neck paragangliomas/pheochromocytomas." (PMID 28187001, 2017). "Germline mutations in the succinate dehydrogenase (SDHA, SDHB, SDHC, SDHD, SDHAF2) or Von Hippel-Lindau (VHL) genes cause hereditary paraganglioma/pheochromocytoma." (PMID 28099933, 2017). "Genomic analysis of familial PGL/pheochromocytoma (PCC) has shown that while mutations of SDHD and SDHC are associated with PGL1 and PGL3, mutations in the large subunit genes SDHB, SDHA and SDHAF2 are associated with PGL4, PGL5 and PGL2." (PMID 35382567, 2022). "Familial CPGLs occur as hereditary paraganglioma/pheochromocytoma (PGL/PCC) syndromes, including PGL1, PGL2, PGL3, PGL4, and PGL5, which are associated with germline mutations in the SDHD, SDHAF2, SDHC, SDHB, and SDHA genes, respectively." (PMID 32971818, 2020). "Mutations in SDHA, SDHB, SDHC, SDHD and SDH assembly factor 2 (SDHAF2) have been identified in hereditary paragangliomas (hPGLs) and pheochromocytomas (PCCs)." (PMID 28748451, 2018). "Cluster 1 PPGLs include pheochromocytomas and abdominal paragangliomas carrying the highest risk of metastatic spread, especially the TCA cycle aberrant tumors carrying genetic variants in enzymes regulating the TCA cycle, including SDHA, SDHB, SDHAF2, FH, MDH2, ISH1 and SLC25A11." (PMID 35205664, 2022). "Familial HNPGLs together with pheochromocytomas (PCCs) account for about 40% and are associated with four types of hereditary paraganglioma syndromes (PGL1–5) caused by mutations in the following genes: SDHD (PGL1), SDHAF2 (PGL2), SDHC (PGL3), SDHB (PGL4), and SDHA (PGL5)." (PMID 33391357, 2020). "Familial pheochromocytoma and paraganglioma syndromes are autosomal-dominant disorders caused mostly by germline mutations in the succinate dehydrogenase subunit (SDH) genes, such as SDHB, SDHC, SDHD, SDHA, and SDHAF2 (succinate dehydrogenase complex assembly factor 2)." (PMID 31443481, 2019).
head and neck paraganglioma (9 papers, 2009 to 2025). A benign or malignant extra-adrenal paraganglioma arising from paraganglia in the head and neck. "It is currently assumed that SDHAF2 variants exclusively cause benign and often multicentric head and neck paragangliomas." (PMID 38549682, 2024). "An even rarer cause for head-and-neck paraganglioma is the SDHAF2 mutation, which should be considered if SDHD, SDHB, and SDHC testing is negative." (PMID 29166454, 2017). "To date, loss-of-function mutations in SDHAF1 (biallelic) and SDHAF2 have been associated with infantile leukoencephalopathy and head and neck paragangliomas, respectively." (PMID 28738844, 2017). "A SDHAF2 loss-of-function mutation (p.Gly78Arg) has been reported in two unrelated families with head and neck paragangliomas." (PMID 28738844, 2017). "Inactivating mutations in the SDHAF2 gene has recently been recognised to cause a rare type of familial paraganglioma syndrome which causes head-and-neck paragangliomas, exclusively in children of fathers carrying the defective gene." (PMID 29166454, 2017). "The G78R mutation in succinate dehydrogenase complex assembly factor 2 (SDHAF2) was identified in a head and neck paraganglioma." (PMID 26462158, 2015).
breast carcinoma (3 papers, 2018 to 2025). "Case #10 with P/LP variants in CHEK2 and SDHAF2 variants had a mixed phenotype with endometrial and breast cancer." (PMID 40943312, 2025). "SDHAF2 is essential for flavinylation and complex II assembly in vivo, but intriguingly, one study in a human breast cancer cell line showed that KO of SDHAF2 still resulted in formation of complex II containing covalent FAD." (PMID 36089066, 2022). "Nevertheless, it is reported that in some thermophilic Archaea and mammalian breast cancer cells that SdhE/SDHAF2 are not required for flavinylation." (PMID 36089066, 2022).
gastrointestinal stromal tumor (3 papers, 2019 to 2022). "Heterozygous germline mutations in SDH complex (SDHx) genes (SDHA, SDHB, SDHC, SDHD, and SDHAF2), which act as tumor suppressor genes, predispose to pheochromocytomas and paragangliomas (PPGLs) and rarely to gastrointestinal stromal tumors (GIST), renal cell carcinoma, and pituitary adenomas." (PMID 35892689, 2022).
pituitary adenoma (3 papers, 2015 to 2019). "Known pheo/PGL genes (SDHA-D, SDHAF2, RET, VHL, TMEM127, MAX, FH) and pituitary adenoma genes (MEN1, AIP, CDKN1B) were sequenced using next generation or Sanger sequencing." (PMID 25494863, 2015).
renal cell carcinoma (3 papers, 2022 to 2025). "Mutations in protein subunits of succinate dehydrogenase (SDHA/SDHB/SDHC/SDHD and assembly factor SDHAF2) and fumarate hydratase (encoded by the single gene FH) lead to rare forms of renal cell carcinoma (RCC; denoted by SDHRCC and FHRCC, respectively)." (PMID 35288096, 2022).
multiple endocrine neoplasia (2 papers, 2022 to 2023). Multiple endocrine neoplasia (MEN) is a group of rare inherited cancer syndromes characterized by the development of two or more endocrine gland tumors, sometimes with tumor development in other tissues or organs. "Examples of PPGLA mutations include the RET gene in multiple endocrine neoplasia (MEN) syndromes, the VHL gene in von Hippel–Lindau disease, the NF1 gene in Neurofibromatosis type 1, the MAX gene, or the genes of the succinate dehydrogenase complex (SDHB, SDHD, SDHA, SDHC, SDHAF2)." (PMID 36010170, 2022).
pheochromocytoma and paraganglioma (2 papers, 2017 to 2021). "The majority of hereditary pheochromocytoma and paraganglioma (PPGL) is caused by germline mutations in the SDHB, SDHC, or SDHD genes, which encode three (SDHB, SDHC, SDHD) of five subunits of succinate dehydrogenase (SDH) enzyme (SDHA, SDHDB, SDHC, SDHD, SDHAF2)." (PMID 34356532, 2021).
cervical cancer (1 paper, 2019). A primary or metastatic malignant neoplasm involving the cervix. "Four characteristic genes, HSPA14, SDHAF2, CAMKK2 and TM9SF1, that can be used as prognostic markers for cervical cancer were selected." (PMID 31744495, 2019).
cholangiocarcinoma (1 paper, 2022). A carcinoma that arises from the intrahepatic biliary tree (intrahepatic cholangiocarcinoma) or from the junction, or adjacent to the junction, of the right and left hepatic ducts (hilar cholangiocarcinoma). "To determine the role of 4-key-genes in cholangiocarcinoma CSCs, we first knocked down SDHAF2, MRPS34, MRPL11 and COX8A in HCCC9810 cell and overexpressed them in RBE cell, respectively." (PMID 35841118, 2022). "In our study, we demonstrated that CSCs in cholangiocarcinoma have different methionine metabolic features, and 4-key-genes (SDHAF2, MRPS34, MRPL11 and COX8A) could promote ICC stemness in a MAT2A-dependent manner." (PMID 35841118, 2022).
chronic myelogenous leukemia (1 paper, 2025). "We generated SDHAF2 knockouts in three different cell lines: the immortalized human embryonic kidney–derived HEK293T (human embryonic kidney–293T) cell line, eHAP, and HeLa cell lines derived from chronic myelogenous leukemia and adenocarcinoma, respectively." (PMID 40815660, 2025).
lymph node metastasis (1 paper, 2022). "Since multivariate analysis suggested that CA19-9, tumor size, lymph node metastasis, SDHAF2, MRPL11 and COX8A are independent factors for OS of ICC patients with adjuvant TACE, a nomogram that included all these risk factors was constructed (C-index: 0.85, 0.81–0.89)." (PMID 35841118, 2022). "In addition, multivariate analysis showed that SDHAF2, MRPL11, COX8A, serum carbohydrate antigen 19-9 (CA19-9), tumor size and lymph node metastasis are independent factors for overall survival (OS) of ICC patients with adjuvant TACE." (PMID 35841118, 2022).
Lynch syndrome (1 paper, 2025). An autosomal dominant hereditary neoplastic syndrome characterized by the development of colorectal carcinoma and a high risk of developing endometrial carcinoma, gastric carcinoma, ovarian carcinoma, renal pelvis carcinoma, and small intestinal carcinoma. "Five cases exhibited combinations of HBOC and endocrine or Lynch syndrome genes (e.g., SDHAF2, SDHA, MSH6)." (PMID 40943312, 2025).
neuroblastoma (1 paper, 2025). Neuroblastoma (NB) is the most common solid, extracranial childhood tumor. "This makes it tempting to extrapolate a similar mechanism being present in neuroblastoma-derived SK-N-SH and SH-SY5Y cells that both accumulate SDHAF2 in response to antimycin A treatment and have other metabolic characteristics of OXPHOS-adapted cells such as spare respiratory capacity." (PMID 40815660, 2025). "Moreover, the accumulation of SDHAF2 following OXPHOS insult is notably absent in some cell lines (HeLa, eHAP, 143B, MCF7, undifferentiated H9 hESCs) but not others (HEK293T, SK-N-SH, SH-SY5Y neuroblastoma cell lines, and hESC-differentiated cardiomyocytes)." (PMID 40815660, 2025).
neurofibromatosis syndrome (1 paper, 2022). "Two nonsyndromic patients (cases 1 and 2) were negative to germline mutations in genes VHL, SDHB, SDHC, SDHD, SDHAF2, TMEM127, and MAX, while the third case (case 3) had clinical diagnosis of neurofibromatosis syndrome." (PMID 36187102, 2022).
tumor (15 papers, 2009 to 2026). "A functional unit, SDH complex assembly factor 2 (SDHAF2), which is encoded by the SDHAF2 gene, has tumour-suppressive effects." (PMID 35382567, 2022). "Unexpectedly, SDHAF2 levels remained unchanged in all four tumor-derived cell lines following antimycin A treatment." (PMID 40815660, 2025). "While SDHB (1p36) and VHL (3p25) are associated with autosomal dominant disease, SDHD (11q23) and SDHAF2 (11q13) show a remarkable parent-of-origin effect whereby tumor formation is almost completely dependent on paternal transmission of the mutant allele." (PMID 28099933, 2017). "The results show that tumorigenesis in SDHAF2-related tumors are fully compatible with the Hensen model, and that 11p loss is less important in SDHB-related tumors than for the other three tumor subgroups." (PMID 28099933, 2017). "SDHAF2 is encoded by SDHAF2 gene which, similar to genetic defects in other SDH gene defects can cause familial catecholamine-hypersecreting tumours." (PMID 29166454, 2017). "Pathogenic variants of SDHD and SDHAF2 confer a remarkable parent-of-origin tumour risk, in which paternally inherited variants cause tumours but maternally inherited variants do not." (PMID 41915642, 2026). "Additionally, studies suggest that high expressions of CYFRA 21-1 and IL-6 in tumor tissue, IL-17 surrounding tumor cells, and the genes SDHAF2, MRPS34, MRPL11, and COX8A in cancer stem cells are associated with a poor prognosis, thus offering novel prognostic avenues for exploration." (PMID 39170710, 2024). "Our results lend further support to the notion that loss of an as yet unidentified locus (or loci) in 11p15 could contribute to tumor formation in SDHD, SDHAF2 and VHL-related PGLs/PCCs." (PMID 28099933, 2017). "The one SDHAF2-related tumor without LOH for chromosome 11 by microsatellite marker analysis, demonstrated normal methylation of both H19-DMR and KvDMR, comparable to blood DNA." (PMID 28099933, 2017). "Given that the accumulation of SDHAF2 in HEK293T cells is not a transcriptional response, this suggests that HeLa and likely the other tumor-derived cell lines may be unable to dynamically increase CII biogenesis." (PMID 40815660, 2025).
cancer (11 papers, 2016 to 2025). A tumor composed of atypical neoplastic, often pleomorphic cells that invade other tissues. "In contrast, of the small number of MAX mutation carriers, 9% (1/11) had a malignant tumor, with the only SDHAF2 mutation carrier being devoid of malignant disease." (PMID 28752085, 2017). "SDHAF2 moonlights as a component of the SDHA-AF2 species of complex II-low, which is associated with altered metabolic signaling in cancer cell lines." (PMID 37119852, 2023). "Succinate dehydrogenase 5 (SDH5), which is also known as SDHAF2 and required for the flavination of succinate dehydrogenase, has been reported to contribute to the development of several types of cancers 17-19." (PMID 31588224, 2019). "Indeed, the subassembly of complex II containing SDHA and SDHAF2 can be observed in cancer cells." (PMID 36089066, 2022). "Despite original reports on the essentiality of SDHAF2 in flavination of CII catalytic subunit SDHA and its established role in heritable paraganglioma, CRISPR-Cas9–mediated knockout studies using popular human cancer-derived cell lines showed that flavination of SDHA occurs in its absence." (PMID 40815660, 2025).
head and neck tumors (1 paper, 2021). "Amongst the four subunits of the SDHx and SDHAF2 genes that lead to paraganglioma syndromes (PGL) types 1 to 5, the highest risk of developing head and neck tumors is seen in relation to SDHD (PGL1) and SDHAF2 (PGL2)." (PMID 34072806, 2021).
infection (1 paper, 2023). The state of being infected such as from the introduction of a foreign agent such as serum, vaccine, antigenic substance or organism. "The detection of increased SDHAF2 indicates the biogenesis of functional CII of the respiratory chain upon infection with A. baumannii AB_1372." (PMID 37052493, 2023). "However, SDHAF2 increased the most (2.1-fold) compared to the control upon infection with AB_1372." (PMID 37052493, 2023). "Notably, SDHAF2, an assembly factor of CII, increased 7.1-fold upon infection with AB_2778." (PMID 37052493, 2023).
SDHAF2 also shares sentences with these, for which no sentence is quoted: neurofibromatosis type 1 (3 papers); genetic diseases (2); kidney carcinoma (2); lung carcinoma (2); multiple endocrine neoplasia type 2 (2); tumor predisposition syndrome (2); Von Hippel Lindau syndrome (2); adenocarcinoma (1); adrenocortical adenoma (1); autosomal dominant disease (1); Costello syndrome (1); Familial adenomatous polyposis (1); hereditary tumor syndromes (1); lung adenocarcinoma (1); Marfan syndrome (1); mitochondrial disease (1); neuroendocrine tumors (1); non-small cell lung carcinoma (1); oligospermia (1); polycythemia (1); salivary duct carcinoma (1); sarcoma (1); somatostatinoma (1); tuberous sclerosis (1).